MYC (MYC proto-oncogene, bHLH transcription factor)
Diseases named in the same sentence as MYC in open-access papers (continued):
Sharing a sentence is not in itself a finding about the gene and the disease.
tumor (continued). "An association was also observed between c-MYC GCN gain and tumour location (P = 0.056, P = 0.042 and P = 0.083 for the amplification status, GCN gain and ASCO/CAP criterion, respectively)." (PMID 28764718, 2017). "High levels of MYC expression in tumor cells drives the overexpression of MCTs, enabling efficient uptake of 3BP and enhanced lethality of the tumor cells in response to this drug." (PMID 28362357, 2017). "The dynamic balance between oncogene-dependent and oncogene-independent tumor growth is explored further in this review, with a specific focus on the role of MYC in cancer cell biology." (PMID 28362357, 2017). "In sensitive breast cancer cell models, Trastuzumab and Lapatinib blocked extracellular signal-regulated kinases 1/2 and phosphatidylinositol-3 kinase (PI3K)/AKT that in turn inhibited MYC activation and upregulated miR-16, a novel tumor suppressor." (PMID 28696357, 2017). "We showed common downstream effects of ESC-like signatures that are shared among heterogeneous HR-NB tumours that are frequently dysregulated by MYC proteins in the same signalling pathway." (PMID 28246384, 2017). "A significant inverse correlation was found between the relative MYC expression in tumor tissues in comparison with their corresponding ANCTs and disease stage." (PMID 28480695, 2017). "Taken into account published data from other tumor forms, our results suggest that MYC overexpression render also SCLC cells dependent on glutaminolysis for growth and survival at both normoxia and hypoxia." (PMID 28430666, 2017). "We next examined the role of SFN/miR-214/c-MYC signaling in tumor spheroid formation and CD133 surface marker expression that are surrogates for CSCs of NSCLC." (PMID 28076844, 2017). "Our finding that a coordinated interplay between the components of the DNA methylating machinery contributes to MYC-driven tumor maintenance highlights the potential of specific DNMTs for targeted therapies." (PMID 29100357, 2017). "The oncogene c-MYC has been known to be involved in tumor formation in chimeric mouse-derived iPSCs." (PMID 28595633, 2017). "ASCL2/MYC tumours displayed the lowest immune infiltration, in contrast to the highly inflamed tumours of the ECM/EMT group showing a maximal tumour purity of 50%." (PMID 28186126, 2017). "MYC, a global regulator of gene expression, is frequently amplified in a large number of tumours (10% of LUADs) and plays a prominent role in tumorigenesis." (PMID 28205554, 2017). "In fact, both mechanisms are essential for MYC-driven tumor initiation and maintenance, and both mechanisms depend on the recruitment of chromatin modifying co-factors." (PMID 28505071, 2017). "Experimentally, inactivation of MYC in genetically engineered conditional mouse tumor models, induced tumor regression when host immunity was intact." (PMID 29163537, 2017). "A positive correlation was observed between the expression of YAP1 and the expression of proliferation-related genes (KI67 and c-MYC) in tumor specimens." (PMID 28036290, 2017). "Utilizing the T-ALL mouse model, we previously reported that tumors depend on the continuous expression of MYC and undergo tumor regression upon inactivation of the oncogene, thereby exhibiting oncogene addiction." (PMID 29100357, 2017). "Double minute chromosomes and homogeneously stained regions have been identified in several tumor types and are biologically complex extrachromosomal entities frequently harboring known oncogenes (i.e MYC) and/or oncogenic fusions." (PMID 28056866, 2017). "Since our in vitro results showed that Menin affected the metabolism and proliferation of HT1080 cells in an MYC-dependent manner, we next studied if Menin regulated tumour growth in vivo." (PMID 28474697, 2017).
tumor (continued). "Identification of MYC target genes is essential in isolating signaling pathways that drive tumor development." (PMID 28696357, 2017). "Such functionally defined luminal progenitors can be transformed by distinct sets of genetic perturbations (i.e., AR+AKT/ERG or c‐MYC+PTEN knockout) to form tumor glands." (PMID 28297567, 2017). "HUGL-1 appears completely released from the membrane, YAP shows cytoplasmic and nuclear enrichment, c-MYC is overexpressed and a number of stromal cells at the tumour-stroma interface are positive to Cas3 (arrowheads in I i.s.)." (PMID 28974715, 2017). "Taken together, this indicates that DNMT3B function is required for MYC-driven tumor maintenance in T-ALL." (PMID 29100357, 2017). "Secondly, MYC referred to invasive biological behavior, including larger tumor size, high histologic grade, lymph node metastasis, positive Ki67 status." (PMID 29212204, 2017). "Similar phenotypes were observed in colon-derived liver metastasis, where HUGL-1 is delocalised, YAP is abundant in the cytoplasm and stains some cell nuclei and c-MYC-positive tumour cells enclose Cas3-positive stromal cells (O arrowheads i.s.)." (PMID 28974715, 2017). "MYC causes overexpression of HDAC2, contributing to tumor cell proliferation, while inactivating mutations in HDAC2 reduce the frequency of tumors in mice." (PMID 28505071, 2017). "Further verifying the importance of MYC activity in pRCC Type 2, a cross species analysis of mouse MYC tumours with the TCGA KIRP data set demonstrated co-clustering of MYC tumours with human papillary Type 2 tumours." (PMID 28593993, 2017). "We identify MYC as a key regulator of the cellular stress responses and tumor cell viability as MYC expression was suppressed in drug-sensitive but not resistant cells." (PMID 28152508, 2017). "It has been shown that complete tumor clearance following the inactivation of MYC oncogene requires the secretion of thrombospondin-1 and the recruitment of CD4+ T cells." (PMID 28333115, 2017). "As expected, metformin significantly decreased the relative mRNA levels of JAK, STAT3 and c-MYC in tumor tissues." (PMID 29088816, 2017). "As among the most frequently amplified oncogenes, MYC was amplified and overexpressed in a wide range of tumor tissues." (PMID 28377632, 2017). "Recent studies indicated that PVT1 RNA and MYC protein expression correlated in primary human tumours, and copy number of PVT1 was co-increased in more than 98% of MYC copy number-increased cancers." (PMID 28404954, 2017). "To note, SRSF1 was also found to regulate MYC by promoting the inclusion of exon 12a in the tumour-suppressor BIN1, known to bind MYC and reduce its oncogenic activity." (PMID 28374191, 2017). "Patients in the MBGrp3 with non-MYC amplified tumours were at high risk, with progression-free survival similar to that for the MBGrp4-HR subgroup (51 [91%] of 56 patients; 46% [95% CI 33–64] for MBGrp3 with non-MYC amplified tumours vs 41% for MBGrp4-HR)." (PMID 28545823, 2017). "Compared with normal counterparts, the MYC mRNA expression level was increased significantly in 74.4% (29 of 39) of tumor tissues." (PMID 29084575, 2017). "Collectively, our data suggest that dinaciclib will probably have single-agent anti-tumour activity against a subset of SCLC that either carry c-MYC amplification or are MCL-1-addicted." (PMID 28714472, 2017). "In particular, metabolic stress required to support continued tumor growth is a potent vulnerability of tumors driven by MYC or RAS." (PMID 28362357, 2017). "The requirement of MYC for tumor cell proliferation has led to an interest in developing compounds that inhibit MYC." (PMID 29163823, 2017).
tumor (continued). "MYC amplification was observed in 4/6 tumours, once clonally, once in a clone only present in IDC and twice only in a clone present in IC." (PMID 28067867, 2017). "The neurospheres isolated from xenografted tumours exhibited similar epigenetic and phenotypic characteristics compared to the primary tumour, and the neurospheres were highly sensitive to treatment with the MYC inhibitor JQ1." (PMID 28417956, 2017). "Double-hit lymphomas (DHL) are rare high-grade neoplasms characterized by two translocations: one involving the gene MYC and another involving genes BCL2 or BCL6, whose diagnosis depends on cytogenetic examination." (PMID 28061782, 2017). "This facilitates survival of eBL tumor cells with the IGH/MYC chromosomal translocation and promotes MYC-induced cell cycle progression, initiating eBL lymphomagenesis." (PMID 29132323, 2017). "Fueling the oncogene’s enigmatic reputation further and intensifying research interest, recent reports reveal that MYC deregulates large gene expression programs in tumor cells through transcriptional amplification." (PMID 28505071, 2017). "Dormant tumor cells are also found when depleting MYC in some tumor types, including epithelial mammary and hepatocellular tumors." (PMID 28333115, 2017). "Dual-treatment strategies with ML327 and bromodomain inhibitors offer the potential both for additive MYC blockade and the potential tumor suppressor effects of E-cadherin." (PMID 29207623, 2017). "MYC gene mis-expression also often arises after failed therapies and then presumably promotes tumor recurrence." (PMID 28333115, 2017). "We showed herein that there possibly exists a new mechanism in which a DLBCL associated circulating miRNA signature suppresses JUN signaling before tumor formation while promoting MYC oncogenic factors." (PMID 28107482, 2017). "Above findings suggested that a complex interplay of DNMTs is required for MYC-driven tumor maintenance." (PMID 29100357, 2017). "Of the 14 tumor tissues with positive p65 expression, 6 were positive for MYC and 9 were positive for BCL-2." (PMID 28039454, 2017). "PP2A-B56α has been shown to play a tumor suppressor role and to negatively control c-MYC stability and activity." (PMID 29190822, 2017). "RNAseq of the mouse tumours demonstrate that MYC tumours resemble Type 2 pRCC, which are known to harbour MYC activation." (PMID 28593993, 2017). "One study showed that only three reprogramming factors (OCT4, SOX2, KLF4), excluding c-MYC, enabled mouse or human somatic cells to be reprogrammed into iPSCs, resulting in a decrease in tumor formation compared to reprogramming with the four factors." (PMID 28595633, 2017). "Experiments with nude mice carrying xenograft tumors showed that SFN sensitized NSCLC cells to cisplatin's efficacy, which is accompanied by inhibition of cisplatin-induced c-MYC accumulation in tumor tissues." (PMID 28076844, 2017). "We further divided the 48 patients into two groups by the median value of relative MYC transcript levels in tumor tissues compared with the corresponding ANCT: high (n=14) and low (n=34) expression groups." (PMID 28480695, 2017). "The region shows high conservation between human and mouse and contains multiple MYC enhancers that are activated in tumor cells." (PMID 28583252, 2017). "Although hyperactive MYC would induce uncontrollable cell proliferation and tumor formation, MYC hyperactivation has been shown to also impose a stress on proper mitotic progression." (PMID 29340052, 2017). "Innovatively—in terms of cancer biology, our results highlight MYC and PRC2 as stem-cell-associated, tumor-specific regulators in pediatric HR-NB." (PMID 28984200, 2017). "Conversely, LEF1 can repress the transcription of MYC and thus act as a tumor suppressor in a subset of human T-ALL cases." (PMID 27965462, 2017).
tumor (continued). "The heightened glycolysis and glutaminolysis in proliferating macrophage is reminiscent of metabolic features in tumor cells, where metabolic reprogramming is driven by aberrant MYC signaling." (PMID 28245597, 2017). "Higher tumor incidence was accompanied by reduced P21 and upregulated c-MYC expression in the tumors." (PMID 28134936, 2017). "We selected the physical interaction of MYC with NSD3 for validation, and uncovered a potential positive regulatory function for NSD3 in activating MYC, implicating the BRD4-NSD3-MYC pathway as a potential target for interrogating MYC-driven tumours." (PMID 28205554, 2017). "One view is that EBV increases the survival of BL tumour cells following the c-MYC translocation event, as evidenced by the original finding that EBV-positive BL cell lines are more resistant to apoptosis than isogenic EBV-negative counterparts." (PMID 28893938, 2017). "The ensuing high MYC levels are not only able to drive tumor initiation, progression, and recurrence, but are also necessary for tumor maintenance." (PMID 28333115, 2017). "MYC regulates the expression of more than 15% of all human genes and orchestrates proliferation, differentiation, self-renewal, apoptosis, and anti-tumor immunity." (PMID 28607447, 2017). "Strikingly, CX-5461 in combination therapy with the pan-PIM kinase inhibitor CX-6258, led to a reversion of Hi-MYC tumours back to high-grade intraepithelial neoplasia." (PMID 28117679, 2017). "In these mice, low-level MYC expression alone is insufficient to drive tumor formation, however, deregulated MYC expression accelerated mutant KRAS-induced lesion formation." (PMID 29170413, 2017). "Average tumor latency was reduced by two to three months in c-MYC/HBx mice compared to single c-MYC transgenic animals." (PMID 28422055, 2017). "Accordingly, we next looked at a potential relationship between 14q32 miRNAs expression and cancer stem cell markers, and we examined the expression of CD44, ABCG2, ALDH1A1, NANOG and c-MYC genes in 53 tumor samples." (PMID 27980227, 2017). "Recently, a subsequent study using different genetically engineered mice showed that the MYC’s binding partner MIZ-1 protein plays a pivotal role in determining the tumor identity." (PMID 28333115, 2017). "FBXW7 is a tumor suppressor that regulates degradation of oncogene proteins such as MYC, cyclin E, Notch, and MCL1." (PMID 28464881, 2017). "MYC overexpression adds to the existing oncogenic gene expression profile by enhancing the activity of already active genes in tumor cells." (PMID 28375188, 2017). "The in vitro and in vivo inhibition of JAK1/2 by ruxolitinib abolished the macrophage-induced tumor proliferative effects and decreased MYC expression." (PMID 29207662, 2017). "The mRNA expression of oncogenic proteins STAT3, IGF1, cyclin D2, and c-MYC increased with respect to increasing glucose concentrations while FOXO1 (tumor suppressor) showed decreased mRNA expression." (PMID 28114390, 2017). "This means that in the tumour types analysed, Cas3 signal in the stromal compartment was highly correlated to c-MYC protein levels in the tumour parenchyma, supporting the existence of a basic signature of MMCC in human cancers." (PMID 28974715, 2017). "In contrast, constitutively high MYC levels in tumor cells drive the expression of DNMT1 and DNMT3B." (PMID 29100357, 2017). "It is apparent that KAT2A and MYC are indeed overexpressed in PRAD tumours compared to normal prostate tissue." (PMID 28592290, 2017). "Since many tumors depend on ('are addicted to') high MYC levels, inhibition of proteins encoded by this class of target genes can be a rational strategy for selective inhibition of MYC-dependent tumor growth." (PMID 27460974, 2016). "Together, these results indicate that the MYC 3′ WRE promotes CRC cell proliferation and tumor growth by driving MYC expression." (PMID 27223305, 2016).
tumor (continued). "For instance NPM1c+ interacts, through its unchanged N-terminal domain, with the tumour suppressors p14ARF and Fbw7γ, the major E3-ubiquin ligase targeting c-MYC, which are both translocated in the cytosol and there proteasomally degraded." (PMID 27058426, 2016). "We chose U2OS cells because they have relatively low levels of endogenous MYC, despite being tumor cells." (PMID 27460974, 2016). "We then introduce N-MYC downstream-regulated gene (NDRG) family members as novel oxygen-dependently regulated genes that can manipulate MYC-HIF tumor metabolic pathways and ultimately modify the Warburg effect." (PMID 27447861, 2016). "MYC, one of the four inducible pluripotent stem cell factors, is known to contribute to cancer stemness in cancer cells, including the tumor-initiating ability, chemoresistance, and self-renewal." (PMID 27821172, 2016). "Reference pathology (Prof. T. Pietsch, Bonn) confirmed the histopathological diagnosis and determined MYC amplification in the original tumor sample." (PMID 26883117, 2016). "The oncogenic overexpression of MYC leads to uncontrolled cell proliferation, while MYC inhibition leads to tumor regression and differentiation of cells, in preclinical models." (PMID 27916803, 2016). "Signaling networks of SKBR3 and MDA-MB-435.eB1 cell lines show a major convergence on ERK1/2 after HERV-K knockdown, while the network from SKBR3 (tumor biopsies or cell lysis), showed a centering on MYC." (PMID 27557521, 2016). "The MYC oncoprotein is a transcription factor which plays a pivotal role in carcinogenesis by transcriptional down-regulation of multiple tumor suppressors." (PMID 27409345, 2016). "MYC immunoreactivity was considered positive when the MYC protein was expressed in more than 40% of tumor cells." (PMID 27689743, 2016). "In both BM and spleen there was a progressive reduction in the proportion of B cells in all Vk*MYC subtypes with increasing tumour burden, that reached significance with high-grade disease." (PMID 27599546, 2016). "Mechanisms involved in the reduced tumor cell proliferation included a downregulation of MYC and its target genes." (PMID 27708232, 2016). "Expression of the Flag‐BirA*‐c‐MYC fusion was induced by feeding the animals with tetracycline, resulting in tumor formation." (PMID 27329485, 2016). "Its encoded protein, c-MYC, regulates CAV1 and both promote tumour progression in prostate and colon cancer." (PMID 27852311, 2016). "MYC is heterogeneously expressed in tumor cells and two representative fields from a case were shown here (400×)." (PMID 27821172, 2016). "The mechanisms through which Bptf inactivation suppresses MYC-driven tumour development in vivo need to be studied further." (PMID 26729287, 2016). "To determine the effects of Bptf deletion on tumour development/progression, we used Ela1-Myc mice where c-MYC overexpression is driven by the acinar-specific Elastase 1 promoter." (PMID 26729287, 2016). "Conversely, some genes that are regulated by exogenous MYC in U2OS cells and have low-affinity promoters, like those encoding transmembrane transporters, are also regulated when comparing the tumor to pre-tumor condition in B cell lymphomagenesis." (PMID 27460974, 2016). "Expression of the GLI2A transgene, detected by immunostaining for the MYC epitope tag, was detected only in the disorganized/dysplastic tumor cells." (PMID 26859571, 2016). "Although MYC itself is difficult to drug, tumor cells often exhibit ‘oncogene addiction’ or changes in gene expression and physiology that make them extremely dependent on a specific oncogenic pathway for growth or survival or both." (PMID 27081479, 2016).